RN7SL327P (RNA, 7SL, cytoplasmic 327, pseudogene)
Gene: Miscellaneous RNA gene on chromosome 15 (75,292,706 to 75,292,928, forward strand). Ensembl gene ENSG00000275992.
Homologues: Orthologues: macaque Metazoa_SRP (75% identical), macaque Metazoa_SRP (48% identical), macaque Metazoa_SRP (47% identical), macaque Metazoa_SRP (46% identical), macaque Metazoa_SRP (45% identical), macaque Metazoa_SRP (43% identical), macaque Metazoa_SRP (34% identical), macaque Metazoa_SRP (33% identical), macaque Metazoa_SRP (32% identical), macaque Metazoa_SRP (19% identical), macaque Metazoa_SRP (18% identical), macaque Metazoa_SRP (17% identical), and 2 more. Paralogues in human: RN7SL429P (100% identical), RN7SL489P (100% identical), RN7SL853P (100% identical), RN7SL241P (86% identical), RN7SL214P (83% identical), RN7SL417P (79% identical), RN7SL319P (78% identical), RN7SL469P (76% identical), RN7SL673P (76% identical), RN7SL495P (76% identical), RN7SL628P (76% identical), RN7SL719P (76% identical), and 709 more.